TNF (tumor necrosis factor)
Diseases named in the same sentence as TNF in open-access papers (continued):
Sharing a sentence is not in itself a finding about the gene and the disease.
pyelonephritis (4 papers, 2020 to 2024). An inflammatory process affecting the kidney. "In pyelonephritis, proinflammatory cytokines, such as Tumor Necrosis Factor-α (TNF-α), Monocyte Chemoattractant Protein-1 (MCP-1), Interleukin-6 (IL-6), IL-8 and IL-23, play an important role in mounting the immune response." (PMID 37371050, 2023). "A negative correlation was found between the count of S. aureus in cancellous bone of animals of group OP sampled before the induction of pyelonephritis and the production of TNFα by PBMCs isolated at 48 hours post the induction of pyelonephritis." (PMID 31992837, 2020). "Interestingly, in our model, this type of tolerance needed a second in vivo hit to be shown since TNFα produced following ex vivo stimulation of PBMCs before the induction of pyelonephritis was not different between the OP and the P groups." (PMID 31992837, 2020).
Rapid Eye Movement Sleep Behavior Disorder (4 papers, 2022 to 2025). "Tumor necrosis factor (TNF) inhibition is under investigation as a therapeutic strategy for Parkinson’s disease (PD) and REM sleep behavior disorder (RBD), yet supporting genetic evidence is limited." (PMID 40963744, 2025). "To date, no genes within the TNF pathway have been identified as genome-wide significant loci (p ≤ 5 × 10−) in PD or REM sleep behavior disorder (RBD), a prodromal clinical marker of PD and other synucleinopathies." (PMID 40963744, 2025).
recurrent disease (4 papers, 2018 to 2025). "The objective of this study is to investigate TNFα expression, promoter methylation, and its regulation by miR-130a-3p in patients with relapsing–remitting (RR)MS, evaluating both serum and saliva as potential diagnostic biofluids." (PMID 41480143, 2025).
reovirus infection (4 papers, 2010 to 2021). "Up-regulated expression of AP-1 and STAT after reovirus infection can promote the expression of proinflammatory cytokines and inflammatory cytokines, such as TNFα, IL-12/IL-1β." (PMID 29562634, 2018). "Analogous to treatment with TNFα, a control NF-κB agonist, reovirus infection resulted in equivalent (∼2- to 3-fold) activation of NF-κB-driven gene expression in wild-type and Bid-deficient cells." (PMID 20617182, 2010). "However, activation of NF-κB in primary cardiac myocytes is largely recalcitrant to reovirus infection or treatment with tumor necrosis factor-α, demonstrating only a minimal response relative to cardiac fibroblasts." (PMID 34237110, 2021). "Unlike other NF-κB agonists such as TNFα which rapidly and transiently activate NF-κB, activation of NF-κB following reovirus infection is gradual and sustained and occurs maximally at 6–8 h post infection." (PMID 20617182, 2010).
Resistant Hypertension (4 papers, 2015 to 2021). "Our findings suggestthat TNF-α might mediate, at least in part,vascular damage in resistant hypertension." (PMID 26504819, 2015). "Interestingly, adding a cholinergic analogue, GTS-21 to the whole blood model strengthened the magnitude of TNF suppression compared to RDN alone, suggesting a further potential for anti-inflammatory effects in resistant hypertension by exploring CAP modulation." (PMID 31416428, 2019).
rheumatic heart disease (4 papers, 2016 to 2025). An autoinflammatory condition following an infection with Group A Beta Hemolytic Streptococcus (GABHS), in which the heart is attacked by antibodies formed in reaction to a recent GABHS infection. "Patients with rheumatic heart disease exhibit elevated levels of circulating interleukin-6 (IL-6); IL-8, IL-2 receptor (IL-2R) and tumor necrosis factor α (TNFα)." (PMID 39202692, 2024). "The presence of chronic inflammation is evidenced by the presence of INF-γ, TNF-α, and IL-10 in biopsied valve tissue in patients with rheumatic heart disease." (PMID 27418982, 2016). "Similarly, our study demonstrated that DEX significantly lowered myocardial injury markers (cTnI and CK-MB) and inflammatory markers (IL-8, TNF-α), increasing IL-10 levels in patients undergoing valve replacement for rheumatic heart disease." (PMID 40951900, 2025).
rhinosinusitis (4 papers, 2015 to 2025). "Elevated IL-6 and TNF-α are closely linked to rhinosinusitis severity and outcomes." (PMID 39870748, 2025). "In particular, 1,8-cineol significantly reduced the expression of TNFα, the major regulator of rhinosinusitis disease mediation." (PMID 26207629, 2015).
scoliosis (4 papers, 2017 to 2023). A congenital or acquired spinal deformity characterized by lateral curvature of the spine. "Of relevance to developmental PCP signaling, at the onset of scoliosis in zebrafish lacking the vertebrate-specific PCP component Protein tyrosine kinase 7 (Ptk7), TNF is highly expressed and triggers Il-6 expression." (PMID 37589075, 2023).
scrapie (4 papers, 2012 to 2025). A fatal disease of the nervous system in sheep and goats, characterized by pruritus, debility, and locomotor incoordination. "Several murine models of classical scrapie show that pro-inflammatory cytokines like IL-1, IL-6 and TNF-α, have increased expression at both mRNA and protein levels in brain, peripheral lymphoid tissue and serum at the terminal end stage." (PMID 22805457, 2012). "In fact, together with the knowledge that endogenous IL-1 may be a mediator of neuronal cell death, evidence that IL-1 and tumor necrosis factor (TNF) were increased in the brains of scrapie-inoculated mice points to these mediators as possible contributors." (PMID 41523471, 2025). "AdMSCs were stimulated for 24 h with TNFα, serum starved for 4 h, then plated in inserts above media containing vehicle-only or 1% normal or RML-scrapie brain homogenate." (PMID 36581683, 2022).
seborrheic dermatitis (4 papers, 2011 to 2025). A chronic, inflammatory skin disorder that affects the scalp, central face and skin folds; it is characterized by scaling and itching. "The ELISA analysis revealed that miRNA transfection significantly modulated IL-6, MMP-9, and TNF-α expression levels compared to the control condition, highlighting their therapeutic potential for seborrheic dermatitis." (PMID 40227405, 2025). "We therefore analyzed the expression of these TNF cytokines in AE, seborrheic eczema (SE) and healthy controls (HC)." (PMID 21765951, 2011).
secondary hemophagocytic lymphohistiocytosis (4 papers, 2021 to 2024). Hemophagocytic lymphohistiocytosis due to infections, autoimmune disorders, or underlying malignancies. "CRP: C-reactive protein, PCT: Procalcitonin, TNF: Tumor-Necrosis Factor, H-Score for reactive hemophagocytic syndrome estimates the risk for having reactive hemophagocytic syndrome." (PMID 38557873, 2024).
serous ovarian cancer (4 papers, 2016 to 2023). "Previous work showed that endometrioid ovarian cancers have a higher positive rate of TNF-α (83.3%, 10/12 cases) compared with high-grade serous ovarian cancer (40%, 20/50 cases) on immunohistochemistry staining." (PMID 36831656, 2023). "Finally, we observed a significant decrease in TNF and IL6 production following CK2 inhibition with CX-4945 by ELISA in cell culture supernatant of primary cells derived from ascites of four high-grade serous ovarian cancer patients." (PMID 26871292, 2016).
Simpson-Golabi-Behmel syndrome (4 papers, 2015 to 2021). Simpson-Golabi-Behmel syndrome is a rare X-linked multiple congenital anomalies syndrome, characterized by pre- and postnatal overgrowth, distinctive craniofacial features, variable congenital malformations, organomegaly and an increased tumor risk. "Increasing reports have shown that the loss of BRD4 function recruits bio-active regulators, which facilitate adipocyte formation of 3T3-L1 cells and TNF-α-treated human Simpson-Golabi-Behmel syndrome adipocytes." (PMID 32575577, 2020). "Human Simpson-Golabi-Behmel syndrome (SGBS) adipocytes were treated with NMP or, for comparison, trigonelline, for 5 h before stimulation with tumor necrosis factor (TNF)-α." (PMID 34680177, 2021). "We used human Simpson-Golabi-Behmel syndrome (SGBS) adipocytes and murine 3T3-L1 adipocytes as cell model systems, and pretreated them with 1-100 μmol/L OA, 0.1-20 μmol/L HT or OA plus HT combination before stimulation with 10 ng/mL TNF-α." (PMID 26030149, 2015).
skin abscesses (4 papers, 2017 to 2024). "Tissue destruction in a gingivalis-induced skin abscess model is abolished in TNF-deficient mice, which is consistent with our results." (PMID 28264025, 2017). "In addition, the TNF inhibitors group showed other adverse effects, including cutaneous complications ranging from simple injection site reactions to multiple skin abscesses." (PMID 39480594, 2024).
skin sensitization (4 papers, 2012 to 2024). An immunological response to previous exposure to a substance which results in an inflammatory skin reaction. "After exposing the skin cells to the recycled materials for 48 h, the release of the proinflammatory cytokines IL-18 and TNF-α, which serve as indicators of potential skin sensitization, was measured in the cell culture medium using ELISA, following the manufacturer’s instructions." (PMID 37765629, 2023).
squamous intraepithelial lesion (4 papers, 2013 to 2021). "Firstly, there was limited number of eligible studies in the meta-analysis of the association between TNF-α rs1800629 polymorphism and risk of squamous intraepithelial lesions." (PMID 24015171, 2013). "Therefore, more studies with large sample are needed to give a more precise estimation of the association between TNF-α rs1800629 polymorphism and risk of squamous intraepithelial lesions." (PMID 24015171, 2013). "The limited sample size in the meta-analysis may fail to provide enough statistical power to detect a possible or weak effect of TNF-α rs1800629 polymorphism on squamous intraepithelial lesions." (PMID 24015171, 2013). "The mother of the child ID6B, who had the highest levels of IFN-γ, TNF-α and IL-2, had cervical disease during the entire FU, in which the disease varied from non-squamous intraepithelial lesion (NSIL) to CIN3 with five different HPV genotypes identified." (PMID 24524328, 2014).
stomatitis (4 papers, 2022 to 2026). Inflammation of the oral mucosa due to local or systemic factors. "Stomatitis increases neuronal-derived SP release, which upregulates downstream pro-inflammatory cytokine expression (TNF-α and IL-6) and increases COX-2 expression, which enhances PG production." (PMID 39570913, 2024).
streptococcal infection (4 papers, 2013 to 2021). Any of the several infectious disorders caused by members of streptococcus, a genus of gram positive bacteria belonging to the family Streptococcaceae. "The involvement of TNF-α in the host defense against streptococcal infection was described in previous studies." (PMID 34248949, 2021). "Inhibition of p38 MAP kinase markedly reduced production of TNF-α, suggesting that transcriptional activation of mast cells following transient permeabilization might contribute to the host defense against streptococcal infections via the beneficial effects of TNF-α." (PMID 34248949, 2021). "In this context, Vγ9/Vδ2 T cells and TNF-α appear to be particularly relevant in Gram-negative infections, IL-1β and MMPs in streptococcal infections, and IL-16 and sIL-6R in CNS infections." (PMID 28318629, 2017). "Nevertheless, NK1.1+ cells were negative for TNF-α intracellular staining, suggesting that this cytokine production was generated mainly by cells of the innate immune system within the NK1.1– population during a streptococcal infection." (PMID 28706510, 2017).
sympathetic ophthalmia (4 papers, 2013 to 2021). Sympathetic ophthalmia (SO) is a bilateral granulomatous anterior uveitis usually occurring within the three months following trauma or a surgical procedure involving one eye. "Observation of upregulated TNF-α in the early experimental autoimmune uveoretinitis (EAU) animal model for human autoimmune uveitis, before inflammatory cell infiltration of the retina, suggests a potential mechanism for vision loss in sympathetic ophthalmia." (PMID 23724856, 2013).
testis cancer (4 papers, 2022 to 2024). "Based on the results of detecting 35 apoptosis-related proteins, it can be inferred that IATL is associated with HIF-1α signaling pathways and TNF signaling pathways, triggering downstream signal pathways that affect testicular cancer cell survival." (PMID 39382942, 2024). "Previous work revealed a crucial involvement of IL-6 in testis cancer and multifunctionality of TNFα in terms of apoptosis, cell survival, and inflammation." (PMID 35269507, 2022).
Thiamine deficiency (4 papers, 2021 to 2023). Thiamine deficiency is a condition that occurs due to not enough thiamine (vitamin B1). "Meanwhile, research have shown animal models of thiamine deficiency have revealed increases in the levels of pro-inflammatory markers such as TNF-α." (PMID 38074148, 2023). "Furthermore, thiamine deficiency highly increases inflammatory cytokines such as IL-1, IL-6, and TNF-α." (PMID 37427326, 2023). "Therefore, there might be a potential activation of pro-inflammatory cytokines such as TNF-α and IL-1βupon excessive thiamine deficiency." (PMID 36386232, 2022). "There is also experimental support for elevated peripheral levels of proinflammatory mediators in animal models of thiamine deficiency and in non-alcohol-associated Wernicke’s encephalopathy, including tumor necrosis factor α (TNFα), interleukin (IL)1β, and IL6." (PMID 34067023, 2021).
tic disorder (4 papers, 2020 to 2024). Disorders characterized by recurrent TICS that may interfere with speech and other activities. "According to univariate ANOVAs, children with tic disorders had significantly elevated levels of IL-1β, TNF-α, IL-6 and IL-4 expression, while controls had significantly elevated levels of IL-17 expression." (PMID 38956051, 2024). "We found a significant correlation between serum IL-1β and TNF-α levels in children with tic disorders (****, p < 0.0001)." (PMID 38956051, 2024). "We found that children with tic disorders had significantly elevated levels of IL-1β, TNF-α, IL-6 and IL-4 expression, while we detected lower expression levels of IL-17 in children with tic disorders." (PMID 38956051, 2024). "Apart from TNF-α (p = 0.159) and IL-6 (p = 0.198) among children with tics and IL-17 among controls (p = 0.129, Kolmogorov‒Smirnov test with Lilliefors correction), none of the cytokines conformed to assumptions of normality." (PMID 38956051, 2024). "In our study, children with tic disorders had significantly elevated levels of IL-1β, TNF-α, IL-6 and IL-4 expression, while controls had significantly elevated levels of IL-17 expression." (PMID 38956051, 2024). "Next, we sought to evaluate the correlation between upregulated cytokines (IL-1β, TNF-α, IL-6, and IL-4) in children with tic disorders." (PMID 38956051, 2024). "Serum IL-1β, TNF-α, IL-6, and IL-4 levels were higher in children with tic disorders than in healthy controls, which is in line with the qRT-PCR data." (PMID 38956051, 2024). "Another recent study also divided tic disorder patients into minimal, mild, and moderate-to-severe symptom groups, where only the mild symptom group showed increased TNF-α levels." (PMID 37907857, 2023). "A recent meta-analysis summarizing 25 studies also identified small-to-large effect sizes for increased IL-6 levels and a large effect size for increased TNF-α levels in tic disorder patients." (PMID 37907857, 2023). "A Chinese study on 1724 tic disorder patients also showed that TNF-α among other cytokines increased in levels as symptoms get more severe, although statistical significance was not reached." (PMID 37907857, 2023). "Finally, we compared children with tic disorders and control children in terms of cytokine expression (i.e., IL-1α, IL-1β, TNF-α, IL-6, TGF-β, IL-17, and IL-4) using qRT-PCR." (PMID 38956051, 2024). "Additionally, although not directly about tic disorders, some studies found that OCD patients, which is comorbid with tic disorder, have increased monocytes compared to healthy controls, which in turn release more cytokines including GM-CSF, IL-1β, IL-6, IL-8, and TNF-α." (PMID 37907857, 2023).
type 2 diabetic nephropathy (4 papers, 2011 to 2021). "The aim of this study was to investigate the correlation of the proinflammatory marker tumor necrosis factor-α (TNF-α) and the tubular marker neutrophil gelatinase-associated lipocalin (NGAL) with the progression of the early stage of type 2 diabetic nephropathy (DN)." (PMID 24250725, 2013).
Ureaplasma infection (4 papers, 2012 to 2024). "With infection-related preterm labor resulting from a production of pro-inflammatory mediators, increased levels of TNF-α, IL-1β, and IL-8 may link intrauterine Ureaplasma infection with preterm birth." (PMID 29234642, 2017). "Others have demonstrated that intra-amniotic ureaplasma infection did not result in increased levels of any tested cytokines (IL-1β, IL-1 receptor antagonist, IL-4, IL-6 and TNF-α)." (PMID 22253806, 2012). "Stimulating TNF-α, IL-1β and IL-8 expression, without inducing anti-inflammatory IL-10 and IL-1ra, Ureaplasma infection might push monocyte cytokine responses toward pro-inflammation." (PMID 29234642, 2017).
ventricular tachycardia (4 papers, 2016 to 2024). A disorder characterized by an electrocardiographic finding of three or more consecutive complexes of ventricular origin with a rate greater than a certain threshold (100 or 120 beats per minute are commonly used). "Along with TNF and IL-6, IL-1 (not mature IL-1β) was indicated as a factor involved in delayed repolarization, long QT syndrome, and ventricular tachycardia." (PMID 36341442, 2022).
viral hemorrhagic fever (4 papers, 2011 to 2015). A viral infectious disease caused by RNA viruses in the Arenaviridae, Bunyaviridae, Filoviridae, or Flaviviridae family, and characterized by a severe multisystem syndrome, with damage to the vascular system and hemorrhaging. "The observed cytokine responses would be expected to give rise to lymphohistocytosis (often associated with CCHF), while both IL-6 and TNFα are associated with the increase in endothelial permeability that is common in viral hemorrhagic fevers." (PMID 23083136, 2012). "This study suggested that modulation of the amount of IL-6 and TNF-α can have a positive effect on patients with viral hemorrhagic fevers." (PMID 26226614, 2015). "Whether the role of TNF-α in SFTSV infection is the same as that in other viral hemorrhagic fevers is not known." (PMID 22911786, 2012). "In contrast, the absence of IL-6 and TNF-α production after infection with JUNV might allow the virus to continue to replicate unchecked and thereby achieve the high virus loads and broad tissue dissemination that are indicative of many viral hemorrhagic fevers." (PMID 21572983, 2011).